CALCB (calcitonin related polypeptide beta)
Description:
CALCB/CGRP2 is a peptide hormone that induces vasodilation mediated by the CALCRL-RAMP1 receptor complex. Dilates a variety of vessels including the coronary, cerebral and systemic vasculature. Its abundance in the CNS also points toward a neurotransmitter or neuromodulator role.
Synonyms: CGRP2; CGRP-II; CALC2; FLJ30166
Tractability: Small molecule: a high-quality ligand is known. Antibody: an approved drug acts on it; UniProt places it where antibodies can reach, with high confidence; its Gene Ontology location is reachable by antibodies, with high confidence; UniProt predicts a signal peptide or a membrane-spanning region. PROTAC: a small molecule that binds it is known.
Target class: Secreted protein
Gene: Protein-coding gene on chromosome 11 (14,904,997 to 15,082,342, forward strand). Ensembl gene ENSG00000175868.
Subcellular location: Secreted
Pathways (Reactome):
Signal Transduction: Calcitonin-like ligand receptors; G alpha (s) signalling events
Gene Ontology:
Molecular function: hormone activity; protein binding; calcitonin receptor binding; neuropeptide hormone activity; receptor ligand activity
Biological process: calcitonin gene-related peptide receptor signaling pathway; adenylate cyclase-activating G protein-coupled receptor signaling pathway; intracellular calcium ion homeostasis; regulation of cytosolic calcium ion concentration; signal transduction; calcitonin family receptor signaling pathway
Cellular component: extracellular region
Genetic constraint (gnomAD): Loss-of-function variants: 8 observed, 10.33 expected, observed/expected ratio (o/e) 0.77, 90% interval 0.45 to 1.39. The upper end of that interval is the gene's LOEUF score, 1.39, which puts it in group 5 of 6, group 1 being the genes least tolerant of losing a copy. Missense variants: 176 observed, 170.91 expected, observed/expected ratio (o/e) 1.03, 90% interval 0.91 to 1.17. Synonymous variants: 76 observed, 71.3 expected, observed/expected ratio (o/e) 1.07, 90% interval 0.88 to 1.29.
Homologues: Orthologues: chimpanzee CALCB (99% identical), rabbit CALCB (89% identical), guinea pig Calcb (84% identical), macaque CALCB (79% identical), rat Calcb (75% identical), mouse Calcb (73% identical), dog CALCB (62% identical), zebrafish calca (56% identical), tropical clawed frog calca (35% identical). Paralogues in human: CALCA (60% identical), IAPP (24% identical).
Diseases named in the same sentence as CALCB in open-access papers:
CALCB is named in the same sentence as 40 diseases in open-access papers, as found by Europe PMC text mining. Sharing a sentence is not in itself a finding about the gene and the disease. The quoted sentences say what the papers report.
migraine (13 papers, 2019 to 2025). "Although plasma CALCB levels were negatively associated with migraine risk in the discovery analysis, CALCB levels were positively associated with migraine risk using CSF data." (PMID 38898596, 2024). "Recently, the CALCB region has been identified as a migraine risk locus in a genome-wide association study (GWAS) with over a hundred thousand migraine cases." (PMID 35682830, 2022). "Similarly, our multiethnic meta-analysis results identified variants in CALCB associated with migraine susceptibility." (PMID 34294844, 2021). "Interestingly, the CALCB gene, encoding the proven migraine therapeutic target CGRP, exhibits the best transcriptional memory." (PMID 33155547, 2020). "In druggability evaluation, multiple approved drugs that target CALCB (calcitonin gene‐related peptide 2) for the treatment of migraines were identified." (PMID 38898596, 2024). "OPRM1 emerges as a pivotal hub, instigating the activation of GNAS and GNB1, subsequently influencing proteins such as RAMP1, RAMP2, RAMP3, CALCB, CALCR, and SLC5A2 all implicated in migraine attacks." (PMID 39215033, 2024). "This activation, in turn, influences other proteins like RAMP 1–3, CALCB, CALCR, and SLC5A2, which are implicated in migraine attacks." (PMID 39215033, 2024). "The new risk loci include genes encoding recent migraine-specific drug targets, namely calcitonin gene-related peptide (CALCA/CALCB) and serotonin 1F receptor (HTR1F)." (PMID 35115687, 2022). "Two of the new risk loci contain genes (CALCA/CALCB and HTR1F) whose protein products are closely related to targets of two migraine-specific drug therapies." (PMID 35115687, 2022). "This suggests that it may be important to use nonhuman primate models to study whether the inflammation and inflammatory transcriptional memory of CALCB promote migraine pathogenesis." (PMID 33155547, 2020). "CGRP receptor inhibitors already showed high efficacy in the treatment of migraine, which is presumably caused via CALCA- or CALCB-mediated vasodilatation in the vicinity of the trigeminal ganglia—the only normal tissue type with physiologically high CALCB expression levels found in our analyses." (PMID 30741933, 2019). "CALCB (Calcitonin-Related Polypeptide Beta) is another component related to CGRP, and variations in the CGRP pathway are being explored as potential targets for migraine treatment." (PMID 39215033, 2024).
Ewing sarcoma (5 papers, 2019 to 2023). A small round cell tumor that lacks morphologic, immunohistochemical, and electron microscopic evidence of neuroectodermal differentiation. "It has been found that a secreted peptide encoded by CALCB promotes the growth of Ewing sarcoma." (PMID 34234876, 2021). "Additionally, targeting the CALCB/RAMP1 axis successfully inhibited tumor growth in a study of Ewing sarcoma." (PMID 37055822, 2023). "In Ewing’s sarcoma (EwS) clonogenic/spheroidal growth and tumorigenicity, RAMP1 (receptor activity modifying protein 1) is a crucial receptor in the assembly of the secretory neuropeptide calcitonin-related polypeptide beta (CALCB)." (PMID 33996533, 2021).
diverticular disease (2 papers, 2021 to 2023). A complex disorder characterised by mucosal outpouchings (diverticulae) of the colonic wall which can become infected and inflamed leading to diverticulitis, perforation and bleeding. "Previous GWAS have established a strong association between CALCB and Vitamin D and its involvement in various diseases, including diverticular disease." (PMID 37841410, 2023). "In parallel, common genetic polymorphisms at CALCB have been reported to contribute to diverticular disease that is a common of intestinal neuromuscular function." (PMID 34294844, 2021).
adenoid cystic carcinoma (1 paper, 2021). A malignant tumor arising from the epithelial cells. "The gene frequencies of major genotype of CALCB in adenoid cystic carcinoma of salivary gland and normal control group were analyzed." (PMID 34234876, 2021). "Using the polymerase chain reaction (PCR) technique, the full-length amplification and genotype analysis of CALCB genes were performed in 39 patients with adenoid cystic carcinoma of salivary gland and 158 normal controls." (PMID 34234876, 2021).
anorexia nervosa (1 paper, 2020). A disorder most often seen in adolescent females characterized by a refusal to maintain a minimally normal body weight, an intense fear of gaining weight, a disturbance in body image, and, in postmenarcheal females, the development of amenorrhea. "Within the anorexia nervosa associated genes we studied, CALCB has the most specific expression in the medial parabrachial nucleus in both the adult and fetal human brain data and ranks 2nd and 4th in the fetal and adult lateral parabrachial nuclei respectively." (PMID 32651428, 2020).
Anxiety (1 paper, 2021). Intense feelings of nervousness, tension, or panic often arise in response to interpersonal stresses. "Moreover, it has also been proposed that CALCB may play a role in the development of anxiety and depression, supporting the involvement of this gene in psychiatric disorders." (PMID 35052345, 2021).
chronic pancreatitis (1 paper, 2017). A chronic inflammatory process causing damage and fibrosis of the pancreatic parenchyma. "A majority of the Treg cells were distributed around pancreatic ductal or blood vessels in the tissues with CALCB mutations, while they were scattered in wild-type from chronic pancreatitis." (PMID 28151472, 2017).
colon cancer (1 paper, 2021). "Recent studies have shown that hypermethylation of the CALCB gene promoter is an important marker for the development of malignant tumors such as esophageal cancer, colon cancer, and thyroid cancer." (PMID 34234876, 2021).
Insulin resistance (1 paper, 2022). Increased resistance towards insulin, that is, diminished effectiveness of insulin in reducing blood glucose levels. "Although Chen and his colleagues reported that CALCB was a calcitonin gene-related peptide which was associated with the initial events triggered in T1DM, up to date to our knowledge, there is no more report on CALCB related with insulin resistance and T2DM." (PMID 36368953, 2022).
lung carcinoma (1 paper, 2021). "In lung cancer research, it was found that the CALCB gene polymorphism is associated with the incidence of lung cancer." (PMID 34234876, 2021).
pancreatic adenocarcinoma (1 paper, 2021). "Methylation of CALCA and CALCB is increased in pancreatic adenocarcinoma, and under that condition, p-AKT and p-CREB levels were decreased." (PMID 34394823, 2021).
pancreatic cancer (1 paper, 2021). "Meanwhile, there were twenty-eight CpG island sites in the CALCB promoter region, with a methylation percentage of 57.5% in pancreatic cancer and 11.4% in paracancer tissues determined by BSP." (PMID 34394823, 2021). "However, the mean percentage of CpG island methylation in CALCB was 13.57% in pancreatic cancer which is significantly higher than that in paracancer tissues (4.29%, P = 0.005)." (PMID 34394823, 2021).
pancreatic ductal adenocarcinoma (1 paper, 2021). An infiltrating adenocarcinoma that arises from the epithelial cells of the pancreas. "Here, we show that methylation of CALCA and CALCB in pancreatic ductal adenocarcinoma was significantly higher than that in paracancer." (PMID 34394823, 2021). "In pancreatic ductal adenocarcinoma, 32 patients showed complete methylation of CALCB (50.79%), and 24 patients showed partial methylation (38.10%)." (PMID 34394823, 2021). "For CALCB, there were 88.89% (56/63) patients showing methylation in the CpG island in pancreatic ductal adenocarcinoma, while only 46.03% (29/63) patients showed methylation in the paracancer tissue." (PMID 34394823, 2021).
trisomy 16 (1 paper, 2022). "We analyzed the methylation indices of the promoter regions of 5 DMGs (ANKRD53, TRPV6, GATA3-AS1, SCL13A4, and CALCB) in chorionic villi trophoblasts of miscarriages with trisomy 16 and induced abortions with a normal karyotype using targeted bisulfite massive parallel sequencing." (PMID 35064135, 2022).
vasculitis (1 paper, 2017). "H&E staining showed pancreatic inflammation (fibrosis), vasculitis, and perineural inflammation from pancreatic tissue with CALCB p.Ser30Pro mutation." (PMID 28151472, 2017).
cancer (7 papers, 2019 to 2025). A tumor composed of atypical neoplastic, often pleomorphic cells that invade other tissues. "Hypomethylation of signal transduction-related genes BDNF and CALCB have the potential to lead to a myriad of cellular responses associated with cancer such as cell growth and proliferation, angiogenesis, and inflammation." (PMID 32051475, 2020).
tumor (3 papers, 2019 to 2023). "Thereby, we identified CALCB as being highly overexpressed in EwS compared to most tumor entities and all normal tissues except for trigeminal ganglia." (PMID 30741933, 2019). "Analysis of 2678 gene expression microarrays comprising 50 tumor entities and 71 normal tissue types revealed that CALCB is specifically and highly overexpressed in EwS." (PMID 30741933, 2019). "Although CALCB and RAMP1 were knocked down to low levels as confirmed by qRT-PCR of tumor tissue, the growth-inhibiting effect was more pronounced in the group of the RAMP1 knockdown." (PMID 30741933, 2019).
infection (1 paper, 2015). The state of being infected such as from the introduction of a foreign agent such as serum, vaccine, antigenic substance or organism. "The expression of CALCB in A549 cells with infection by conidia had also downtrend." (PMID 26273834, 2015).
CALCB also shares sentences with these, for which no sentence is quoted: COVID-19 (2 papers); ankylosing spondylitis (1); autoimmune disease (1); Cluster headache (1); Constipation (1); depression (1); esophageal cancer (1); gastrointestinal disease (1); Headache (1); inflammatory bowel disease (1); meningioma (1); migraine with aura (1); osteoarthritis (1); Pain (1); pancreatitis (1); psychiatric disorder (1); rheumatic diseases (1); rheumatoid arthritis (1); salivary gland adenoid cystic carcinoma (1); Sepsis (1); thyroid cancer (1); type 1 autoimmune pancreatitis (1).